LGALS3 (galectin 3)
Diseases named in the same sentence as LGALS3 in open-access papers (continued):
Sharing a sentence is not in itself a finding about the gene and the disease.
Pleural effusion (2 papers, 2017 to 2021). The presence of an excessive amount of fluid in the pleural cavity. "Other interesting biomarkers that have been investigated, are C-C chemokine ligand 2 (CCL2) and galectin-3 (LGALS3), both measured in patients with pleural effusions." (PMID 28881848, 2017).
pregnancy disorder (2 papers, 2021 to 2025). A disorder that is related to pregnancy. "Nevertheless, available data implicate galectin-3 in PE development and further research is needed to determine its role in the pathophysiology of this pregnancy disorder and the potential use of galectin-3 as a biomarker for PE." (PMID 35008499, 2021).
Respiratory tract infection (2 papers, 2016 to 2021). An infection of the upper or lower respiratory tract. "Thus, our aim was to investigate the association of SNPs at LGALS3 and serum GAL-3 levels with Frequency of Respiratory Tract Infection (FRTI) and Frequency of Vaso-occlusive Crisis (VOC) in patients with SCA." (PMID 27603703, 2016).
restrictive lung disease (2 papers, 2022 to 2023). "Indeed, the Framingham Heart study revealed increased blood galectin-3 levels to be associated with restrictive lung disease and interstitial lung abnormalities." (PMID 37932771, 2023).
retinal ischemia (2 papers, 2008 to 2022). A ischemic disease that involves the retina. "Removal of LGALS3 inhibits AGE-mediated retinal ischemia and suggests an important role for LGALS3 in AGE-related pathophysiology." (PMID 18554398, 2008).
scrapie (2 papers, 2016 to 2018). A fatal disease of the nervous system in sheep and goats, characterized by pruritus, debility, and locomotor incoordination. "In a separate study, the protein level of galectin-3 was also found to be increased in scrapie-infected brains." (PMID 29867350, 2018). "Previously, we have reported the change of galectin-3 protein expression in murine prion disease model, scrapie, and showed its correlation with PrPSc accumulation in scrapie." (PMID 27936017, 2016).
secondary progressive MS (2 papers, 2023 to 2024). "Another study identified galectin-3 as a potential antigen recognized by antibodies present in the peripheral blood of individuals with secondary progressive MS (SPMS)." (PMID 39728753, 2024).
seminoma (2 papers, 2019 to 2023). A radiosensitive malignant germ cell tumor found in the testis (especially undescended), and extragonadal sites (anterior mediastinum and pineal gland). "The expression of the Lgals3 gene encoding galectin-3 in seminomas was slightl higher in relation to the tissue unchanged by the carcinogenetic process." (PMID 38144531, 2023). "QRT-PCR analysis showed a significant decrease in the expression of β-catenin and E-cadherin genes and a slight increase in the expression of the Lgals3 gene encoding galectin-3 in the seminomas compared to healthy tissue." (PMID 38144531, 2023). "Nevertheless, we consider the localization of galectin-3 in the endothelium in the seminoma as an obvious manifestation of the participation of the studied protein in the angiogenesis process in carcinogenesis." (PMID 38144531, 2023). "The aim of the study was immunohistochemical identification and evalutaion of adhesive molecules β-catenin, E-cadherin, galectin-3 in testicular cancer – seminoma." (PMID 38144531, 2023). "Our results demonstrated galectin-3 expression in both control tissue and seminoma." (PMID 38144531, 2023). "The results of the study suggest a significant role of β-catenin, E-cadherin and galectin-3 in the carcinogenesis of seminomas and may indicate new aspects of the patomechanism of seminomas formation, and thus time lead to better understand the biology of these tumors." (PMID 38144531, 2023). "While the results concerning β-catenin and E-cadherin were not surprising, the immunoreactivity of galectin-3 and its localization in the seminoma seem to be the most interesting finding in our study." (PMID 38144531, 2023). "Galectin-3 expression, however, was demonstrated in seminomas, with no apparent significant difference compared to control tissue." (PMID 38144531, 2023). "Due to the small amount of scientific reports on galectin-3 in seminoma, it is not easy for us to refer and draw clear conclusions." (PMID 38144531, 2023). "A higher galectin-3 mRNA was observed in the non-seminomas GCT cell line (NCCIT) compared to the seminoma GCT cell line (JKT1)." (PMID 31652641, 2019).
silicosis (2 papers, 2024 to 2025). Silicosis is a respiratory disease caused by breathing in (inhaling) silica dust. "The Fibr-2 macrophage subset likely represents end-stage profibrotic macrophages in the silicosis lung due to waning expression of profibrotic genes coupled with increased expression of foamy macrophage markers including Spp1, Cd36, and lipid-metabolizing genes such as Lgals3 and Lrp1." (PMID 38985878, 2024).
skin tumors (2 papers, 2017 to 2023). "Galectin-3 was increased in TSC-related skin tumors, angiomyolipomas, and lymphangioleiomyomatosis with serum levels in patients with lymphangioleiomyomatosis correlating with impaired lung function and angiomyolipoma presence." (PMID 28695825, 2017).
Sleep apnea (2 papers, 2025). An intermittent cessation of airflow at the mouth and nose during sleep is known as sleep apnea. "The aim of this study was to determine whether galectin-3 levels are related to the severity of sleep apnea." (PMID 39941305, 2025). "In the present study, where we assessed the role of galectin-3 in predicting the severity of OSA, galectin-3 levels were significantly elevated in patients with severe sleep apnea." (PMID 39941305, 2025).
Still’s disease (2 papers, 2024 to 2025). "Chen and colleagues investigated the relationship between galectin-3 levels and disease activity in Still’s disease, an autoinflammatory disease, and reported that galectin-3 levels were elevated in these patients and positively correlated with IL-1β and IL-18 levels." (PMID 41008774, 2025). "Furthermore, the fact that galectin-3 and presepsin levels have been investigated in other autoinflammatory syndromes such as PFAPA and Still’s disease suggests that these biomarkers may be elevated in different diseases." (PMID 41008774, 2025).
Thyroid adenoma (2 papers, 2013 to 2021). The presence of a adenoma of the thyroid gland. "The gene expression data showed that IDD further enhanced the upregulation of Lgals3 caused by neonatal irradiation, which may also be related to the development of thyroid adenoma." (PMID 34880333, 2021). "The co-administration of IDD induced the proliferation and the upregulation in Lgals3 expression, resulting in thyroid adenoma development at 28 weeks post-exposure." (PMID 34880333, 2021).
tuberculosis (2 papers, 2018 to 2020). A chronic, recurrent infection caused by the bacterium Mycobacterium tuberculosis. "In our cohort, galectin-3 appears as a biomarker for LTD and cavity in patients with tuberculosis during initial phase of ATT." (PMID 30687336, 2018).
urothelial carcinoma (2 papers, 2014 to 2024). A malignant neoplasm derived from the transitional epithelium of the urinary tract (urinary bladder, ureter, urethra, or renal pelvis). "Regarding urothelial carcinoma grade, some studies have reported that high-grade tumors exhibit more galectin-3 expression compared to low-grade tumors." (PMID 39451592, 2024).
uterine cancer (2 papers, 2014 to 2024). Primary or metastatic malignant neoplasm involving the uterine corpus and/or the cervix. "Our analysis of LGALS3 expression in the uterine cancer in the TCGA revealed that elevated LGALS3 expression was associated with worse clinical outcome in patients diagnosed with USC." (PMID 38438589, 2024). "The TCGA uterine cancer data set revealed patients with high levels of LGALS3 had a significantly shorter PFS compared to those with low levels of LGALS3) (p = 0.0088)." (PMID 38438589, 2024). "We further showed both membranous and cytoplasmic expression of galectin-3 on single-cell tumor suspensions from primary tumors and on uterine cancer cell lines." (PMID 24658839, 2014).
uveitis (2 papers, 2022 to 2024). An inflammatory process affecting a part of or the entire uvea. "Similarly, galectin-3 inhibition in experimental uveitis may reduce disease severity." (PMID 35711472, 2022).
varicella zoster virus infection (2 papers, 2021 to 2022). "Increased serum galectin-3 has been observed in patients with varicella-zoster virus infection and patients with herpes zoster neuralgia and post-herpetic neuralgia presented with higher concentrations." (PMID 34439802, 2021).
viral hepatitis (2 papers, 2020 to 2025). An acute or chronic inflammation of the liver parenchyma caused by viruses. "High levels of galectin-3 protein were also detected in biliary epithelial cells of patients with viral hepatitis, while galectin-3 was weakly expressed in biliary epithelial cells and sclerosing bile ducts of patients with primary biliary sclerosing cholangitis." (PMID 40649879, 2025).
acute appendicitis (1 paper, 2025). "This profile indicates that while Galectin-3 is unlikely to miss true appendicitis cases (low false-negative rate), it may generate a considerable number of false positives, limiting its stand-alone diagnostic value." (PMID 41234450, 2025).
alcoholism (1 paper, 2023). "In accordance with these observations, among the seven alcoholism causal genes with sex difference in brain protein expression that we identified, LGALS3 is a driver of macrophage and microglia activation and has been implicated in neuroinflammation." (PMID 37653343, 2023).
alexithymia (1 paper, 2021). An agnosia that is a deficiency in understanding, processing, or describing emotions. "The patients with alexithymia did not have higher prevalence of high galectin-3, but had higher median galectin-3 levels (p = 0.005)." (PMID 34045984, 2021).
aortic coarctation (1 paper, 2022). "They found that galectin-3 did not predict persistent left ventricular hypertrophy nor abnormal wall thickness in children after the cardiosurgical treatment of aortic coarctation." (PMID 35410028, 2022).
carcinoid tumor (1 paper, 2019). A slow growing neuroendocrine tumor, composed of uniform, round, or polygonal cells having monotonous, centrally located nuclei and small nucleoli, infrequent mitoses, and no necrosis. "Immunohistologic tests showed positive expression of chromogranin A (CgA), Galectin-3, neuron-specific enolase (NSE), and synaptophysin (Syn), which are biomarkers of carcinoid tumors." (PMID 31770214, 2019).
central nervous system lymphoma (1 paper, 2019). "In contrast, increased serum galectin-3 expression may be associated with worse prognosis in primary central nervous system lymphoma NHL and AML." (PMID 31929803, 2019).
cerebral microbleeds (1 paper, 2022). Cerebral microbleeds are a group of pathological processes affecting the small arteries, arterioles, capillaries and venules of the brain, as detected by brain imaging techniques. "For example, diabetic conditions and resulting cerebral microbleeds encourage the infiltration and aggregation of phagocytic, galectin 3‐expressing macrophages from blood, to assist in the clearance of dysfunctional micro‐vessels." (PMID 35751629, 2022).
cervicitis (1 paper, 2017). An acute or chronic inflammatory process that affects the cervix. "The positive expressions of ezrin and galectin-3 in CIN group were higher than in cervicitis group (both P<0.05), but the differences of positive ezrin expression rate among CIN grade I, II and III were not statistically significant (all P>0.05)." (PMID 28355349, 2017).
chromoblastomycosis (1 paper, 2020). "Then, galectin-3 expression may be used as a diagnostic biomarker of chromoblastomycosis." (PMID 32498471, 2020). "Galectin-3 expression was studied by immunohistochemistry on skin sections of patients suffering chromoblastomycosis." (PMID 32498471, 2020). "During chromoblastomycosis, known as a benign epidermal proliferation, it was suggested that galectin-3 may be an interesting biomarker." (PMID 32498471, 2020).
coagulopathy (1 paper, 2021). "Plasma galectin-3 concentrations after TBI are closely related to trauma severity, inflammation, and acute traumatic coagulopathy." (PMID 33939120, 2021).
colorectal tumour (1 paper, 2007). "Irrespective of this open question, and in line with several reports, galectin-3 still fulfils the criteria of a colorectal tumour marker with a sensitivity of 0.79 and 0.83 and a specificity of 0.97 and 1.00 in primary and metastatic tissue." (PMID 17912244, 2007).
coronary artery aneurysms (1 paper, 2022). "Additionally, the autopsies of the myocardium or coronary artery aneurysms in patients who died or underwent transplantation over the course of Kawasaki disease revealed galectin-3 expression cells." (PMID 35410028, 2022).
cribriform carcinoma (1 paper, 2010). A carcinoma characterized by the presence of a cribriform architectural pattern. "However, we think that the most significant clinically relevant function of galectin-3 is as a marker that can distinguish tubular carcinoma from mucinous and cribriform carcinomas." (PMID 23658855, 2010).
cystinosis (1 paper, 2022). Cystinosis is a metabolic disease characterized by an accumulation of cystine inside the lysosomes, causing damage in different organs and tissues, particularly in the kidneys and eyes. "Interestingly, non-steroidal anti-inflammatory drugs, such as aspirin and indomethacin, have been found to inhibit galectin-3 expression in human macrophages by inhibiting its transcription, which may be partially responsible for the beneficial effects seen with indomethacin in cystinosis patients." (PMID 35053306, 2022).
dengue (1 paper, 2016). "In the bacterial infection group, the level of galectin-3 was higher compared to dengue and healthy control groups." (PMID 27240351, 2016). "The levels of galectin-1, galectin-3, L-selectin and P-selectin in dengue patients were different from those in patients with bacterial infection, but it was not different from those in healthy controls." (PMID 27240351, 2016). "Lower serum levels of galectin-1, galectin-3, and E-, L-, and P-selectin in dengue patients were detected compared to bacteria-infected patients, but not to healthy controls." (PMID 27240351, 2016). "The aim of this study was to investigate the serum concentration and potential interaction of soluble galectin-1, galectin-3, galectin-9, galectin-3 binding protein (galectin-3BP), glycoprotein 130 (gp130), and E-, L-, and P-selectin in patients with dengue fever in acute febrile phase." (PMID 27240351, 2016).
diabetic foot ulcers (1 paper, 2022). "Studies have reported that Galectin-3 is associated with the occurrence of diabetic foot ulcers." (PMID 35083706, 2022). "Galectin-3 promotes blood vessel formation and new blood vessel formation because Galectin-3 increases the level of VEGF-A; thus, Galectin-3 promotes the healing of diabetic foot ulcers (DFUs)." (PMID 35083706, 2022).
diabetic neuropathy (1 paper, 2024). A chronic, pathological complication associated with diabetes mellitus, where nerve damages are incurred due to diabetic microvascular injury involving small blood vessels that supply these nerves, resulting in peripheral and/or autonomic nerve dysfunction. "Background and Objectives: This study aimed to investigate the protective effect of diosmin and hesperidin in diabetic neuropathy using a rat model, focusing on their impact on nerve regeneration through the fibroblast growth factor 21 (FGF21) and galectin-3 (gal3) pathway." (PMID 39459367, 2024).
eczema (1 paper, 2019). "Eczema was associated with decreased concentrations of IFNα, IFNγ, TSLP, CXCL9, and CXCL13, but increased concentrations of CCL18 and Galectin-3." (PMID 31998285, 2019). "In addition, eczema was associated with decreased concentrations of IFNα, IFNγ, TSLP, CXCL9, and CXCL13, but with increased concentrations of CCL18 and Galectin-3." (PMID 31998285, 2019).
edema (1 paper, 2022). An abnormal accumulation of fluid beneath the skin, or in one or more cavities of the body. "It was verified that galectin-3 knockout mice suffered a much more severe onset of FK with higher clinical scores of corneal lesion depth, area, and corneal edema degree compared to the wild-type mice." (PMID 35437453, 2022).
endocrine pancreatic tumors (1 paper, 2013). "Cells from SPTs may also reveal focal immunoreactivity for cytokeratin and synaptophysin, demonstrate abnormal nuclear localization of β-catenin and the presence of progesterone receptors and may express galectin-3, all of which are useful in differentiating SPTs from endocrine pancreatic tumors." (PMID 23384084, 2013).
erythrocytosis (1 paper, 2019). "Besides on thrombocytopenia, Lgals3−/− mice showed erythrocytosis and leukopenia when compared with Lgals3+/+ mice both treated with pristane." (PMID 31601823, 2019).
Fibroadenoma (1 paper, 2012). A benign tumor of the breast characterized by the presence of stromal and epithelial elements. "A weak interaction with ducts, in healthy samples was observed when anti-galectin-3 antibody was used, whereas, in fibroadenoma samples, the interaction was observed in ducts and stromal cells." (PMID 23265237, 2012). "Our results suggest that expression of antigen TF and galectin-3 seems to participate in fibroadenoma development." (PMID 23265237, 2012). "Histochemical and immunofluorescence analysis showed positive expression of galectin-3 in fibroadenoma tissue, mainly in stroma, weak interaction in ducts was observed; whereas, in healthy tissue samples the staining was also weak in ducts." (PMID 23265237, 2012).
hemangioblastoma (1 paper, 2015). "Expression of galectin-3 was correlated with the expression of HIF-1α and VEGF in the development of hemangioblastoma." (PMID 26222311, 2015).
hepatitis C virus infection (1 paper, 2023). A viral infection caused by the hepatitis C virus. "Hepatitis C virus infection increases serum galectin-3 levels, which in turn can promote inflammation and fibrosis progression." (PMID 37958814, 2023).
Hernia (1 paper, 2020). "The results pointed out ACAN, MMPs, COLs, EPYC, VIT, CCBE1 and LGALS3 genes as strong candidates to trigger umbilical hernias in pigs, because they are involved in hernia related biological processes since the embryogenesis." (PMID 32379844, 2020).
herpesvirus infection (1 paper, 2021). "Moreover, in herpesvirus infection, galectin-3 was involved in the regulation of adaptive immunity (it constrained the activation of CD8+ T-cells)." (PMID 34439802, 2021).
HIV-associated neurocognitive disorder (1 paper, 2024). HIV-associated neurocognitive disorder (HAND) remains a common complication of HIV infection in the combination antiretroviral therapy (ART) era. "Further, in the SIV-macaque model of HIV-associated CVD and HIV-associated neurocognitive disorder (HAND), plasma IL-18, in addition to galectin-3 and galectin-9, was shown to correlate strongly with monocyte activation and turnover." (PMID 39201388, 2024).
hypercoagulability (1 paper, 2023). "The evaluation of underlying molecular pathomechanisms by which galectin-3 influences hypercoagulability is a topic of future research." (PMID 37175392, 2023). "In patients with acute respiratory diseases, galectin-3 can be considered as a marker not only for disease severity, but also for increased hypercoagulability." (PMID 37175392, 2023).
hyperhomocysteinemia (1 paper, 2024). A serious metabolic condition caused by mutations in the MTHFR gene, medications, or nutritional deficiency. "Taken altogether, parameters related to H. pylori/MetS, including pericyte dysfunction, hyperhomocysteinemia, galectin-3, AF, and/or gut dysbiosis, may play roles in negative pregnancy and neonatal outcomes." (PMID 38673633, 2024).